IL6 (interleukin 6)
Diseases named in the same sentence as IL6 in open-access papers (continued):
Sharing a sentence is not in itself a finding about the gene and the disease.
Obesity (continued). "Our data suggests that lipotoxicity-dependent IL-6-production and the subsequent inhibition of IKr and IKs underlies adverse ventricular electrical remodeling prior to fatal ventricular arrhythmias acquired in obesity and associated disease pathologies." (PMID 34681909, 2021). "Previous studies have shown that different inflammation biomarkers, such as CRP, TNFα and IL-6, were differently associated with body composition and these may further differ by obesity level and sex." (PMID 33557067, 2021). "Nutritional supplementation with ME7, ME10- and/or exercise training was able to facilitate a lowered circulating concentration of cytokines which have been associated with obesity (including IL-6, IL-7, and IL-8), which was mirrored by lowered mRNA expression of these markers in WAT." (PMID 34835983, 2021). "Circulating serum levels of adiponectin are decreased in patients with obesity, type 2 diabetes, metabolic syndrome, or cardiovascular disease inflammation, and are associated with an increased release of pro-inflammatory cytokines like IL-6 and TNF-α." (PMID 33418879, 2021). "Published literature shows that lotus leaf reduces the levels of inflammatory cytokines IL-1β, TNF-α, IFN-γ, and IL-6, increases the levels of anti-inflammatory cytokines IL-4 and IL-10, and inhibits inflammation caused by high-fat diets accompanied by obesity." (PMID 34992717, 2021). "Thus, obesity is directly associated with low-grade chronic inflammation, as the expression of proinflammatory cytokines (IL-6, IL-8, PCR, and TNF-α) is shown to be increased in this pathology." (PMID 33716759, 2021). "Furthermore, obesity leads to release of pro-inflammatory mediators such as IL-1β, IL-6 and MCP-1, and then causes circulating monocytes recruitment and macrophages accumulation in adipose tissue." (PMID 35185543, 2021). "In addition, obesity promotes inflammation by increasing pro-inflammatory cytokines, such as tumor necrosis factor-alpha and interleukin-6, and increases cardiovascular disease risk." (PMID 33855037, 2021). "Obesity can be inhibited by limiting adipogenesis, which is associated with IL6 expression in mice." (PMID 35126382, 2021). "Moreover, obesity causes inflammation and lipid peroxidation by abnormal production of pro-inflammatory factors such as IL-6 and CRP as well as the release of free fatty acids from adipose tissue." (PMID 33596883, 2021). "Obesity-associated chronic low-grade inflammation characterized by high levels of plasmatic inflammatory markers [C-reactive protein, interleukin 6 (IL6) or tumor necrosis factor α (TNFα)] largely contributes to the development of the obesity-related chronic metabolic diseases." (PMID 35024040, 2021). "The role of IL-6 in NAFLD is closely associated with obesity and insulin resistance." (PMID 34447378, 2021). "Obesity is directly associated with systemic inflammation through its tie with the cytokine IL-6." (PMID 34452063, 2021). "In our study, obesity-induced damage to the female reproductive system is associated with increases in IL-6 and TNF-α mRNA and protein expression levels based on an agreement in the results of IHC staining, Western blotting and quantitative RT-PCR in the HFD female reproductive organs." (PMID 34560886, 2021). "Indeed, obesity is associated with the increased production of pro-inflammatory cytokines, such as interleukin-6 (IL-6) and tumor-necrosis factor α (TNFα), leading to a low chronic inflammatory state." (PMID 34940598, 2021). "Multiple gene polymorphisms of IL6 were studies in terms of obesity risk." (PMID 34207683, 2021). "IL-6 and its receptors are associated with inflammatory processes in the liver in obesity." (PMID 33579000, 2021). "Indeed, obesity is associated with chronic inflammation, with higher circulating inflammatory markers such as interleukin-6 (IL-6)." (PMID 34371858, 2021). "Other mechanisms that could be involved in T2-low asthma are those associated with IL-6 and obesity." (PMID 35055325, 2021).
Obesity (continued). "Therefore, our study aimed at evaluating the circulating levels of IL-6, clusterin and irisin in obese subjects of both sexes who had different grades of obesity and examining their sexual dimorphism and their association with insulin resistance." (PMID 33905632, 2021). "These diseases extend from obesity to so-called “MS,” which leads to the activation of some inflammatory factors, cytokines and chemokines, such as interleukin-6 (IL-6) and C-reactive protein, which are significantly associated with MS and the severity of depression." (PMID 34531719, 2021). "In addition to involvement in neuronal damages in acute stroke, IL-6 has been reported to induce skeletal muscle inflammation-associated insulin resistance and glucose intolerance in obesity." (PMID 34943061, 2021). "Previously, serum levels of soluble TNF receptors were found to be elevated during asthma attacks in atopic and non-atopic subjects, and recent observations of two cohorts of asthmatics found a high IL-6 level to be associated with obesity and a more severe disease phenotype." (PMID 34112152, 2021). "Interestingly, clinical and experimental studies have reported elevated levels of inflammatory cytokines—(interleukin-6 (IL-6), interleukin-1beta (IL-1b), tumor necrosis factor alpha (TNFa)—associated with obesity or HFD consumption." (PMID 34067897, 2021). "Other cytokines that are also associated with obesity and insulin resistance are IL-6 and IL-1β." (PMID 33557218, 2021). "A simultaneous relative increase in IL-6 levels could be observed, which supports previous findings associating women’s obesity and IL-6 elevation." (PMID 34698104, 2021). "Additionally, IL-6 deficient mice develop mature-onset obesity, partially attributed to reduced energy expenditure, and conversely, overexpression of IL-6 leads to increased thermogenesis energy expenditure." (PMID 32878032, 2020). "As expected, obesity was associated to increased inflammation of the ileum, as revealed by the significantly higher mRNA expression level of Il1b, Ccl2 and, to a lesser extent, of Il6." (PMID 32244932, 2020). "The results suggested that proinflammatory levels of IL6 and hyperinsulinemia were higher in underlying obesity with microbial dysbiosis represented by alpha diversity and might be a probable cause of such pathology." (PMID 32927823, 2020). "Interestingly, obesity-associated cytokines like IL-6 and TNF-α are able to influence many signaling pathways and induce defects in the ciliogenesis of ASCs." (PMID 32806722, 2020). "Our results of increased frontal cortex levels of IL6 and IL1β and their strong association with an altered species diversity show that obesity-induced unique microbiome signature might exacerbate the proinflammatory microenvironment in the brain." (PMID 32927823, 2020). "In line with this hypothesis, IL-6 levels are associated with obesity, insulin resistance and type 2 diabetes risk in observational epidemiology studies." (PMID 33096487, 2020). "Indeed, obesity is associated with increased production of pro-inflammatory cytokines, such as interleukin-6 (IL-6) and tumor necrosis factor α (TNFα), leading to a chronic inflammatory state." (PMID 33266209, 2020). "In addition, SO reduced the increased of plasma interleukin-6 (IL-6) levels in Otsuka Long–Evans Tokushima Fatty rats caused by obesity." (PMID 31936134, 2020). "Obesity and insulin resistance, which may cause major health problems per se, are risk factors for AD, and cytokines such as interleukin-6 (IL-6) have a role in these conditions." (PMID 32630818, 2020). "Interestingly, IL-6 trans-signaling has also been implicated in obesity, as sIL-6R is a critical chemotactic signal for adipose tissue macrophages recruitment." (PMID 32630818, 2020). "Furthermore, obesity is associated with high levels of inflammatory cytokines, such as leptin, IL-6, and TNF-α, produced by adipocytes and immune cells infiltrating adipose tissue." (PMID 33343662, 2020).
Obesity (continued). "Studies have suggested that obesity predisposes to the expansion of Th17 cells via IL-6 which may in turn exacerbate inflammatory conditions such as multiple sclerosis." (PMID 32849611, 2020). "A remarkable observation in this context is that TNFR1-mediated activation of JNK, as well as of the oncogenic transcription factor STAT3 and associated IL-6 production promote obesity-related hepatocarcinogenesis, which is also strongly reduced in TNFR1-deficient mice." (PMID 32235829, 2020). "Given the known health risks associated with obesity, it would be of value for clinicians to have reliable information about whether IL-6 signaling inhibitors systematically induce weight gain, in order to aid their decision-making." (PMID 32878032, 2020). "In summary, we demonstrated that the presence of the 6 g spice blend in a HFCM significantly reduced postprandial IL-1β, IL-6, and IL-8 secretion from LPS-stimulated PBMCs in men with overweight/obesity at risk of CVD, suggesting a potential anti-inflammatory effect of spices." (PMID 32211803, 2020). "This is in line with other reports that show that IL‐6 expression is associated with obesity." (PMID 32313680, 2020). "Obesity and in particular central adiposity – the excess deposition of visceral fat – is associated with increased serum levels of pro-inflammatory cytokines such as interleukin 6 (IL-6), C-reactive protein (CRP), and tumor necrosis factor (TNF)." (PMID 32508807, 2020). "From a pharmacological point of view, the intestinal lipase inhibitor orlistat is of particular interest, which helps in weight reduction by decreasing levels of tumor necrosis factor alpha and interleukin 6 and may reduce the risk of obesity and CVD." (PMID 32825823, 2020). "Therefore, high TNFα and IL-6 levels are also associated with MetS risk factors such as obesity, insulin resistance, and T2DM." (PMID 32178436, 2020). "The exact pathophysiological causes are yet to be fully determined, however, circulating levels of cytokines including IL6 have been linked to fatigue and depressed mood, and as IL6 is elevated in both obesity and MPN further illumination of the underlying mechanisms is crucial." (PMID 32781663, 2020). "The findings presented here suggest that while IL‐6 produced by adipose tissue is associated with obesity, systemic levels of IL‐6 may be associated with weight loss and improved insulin sensitivity early after VSG‐induced weight loss." (PMID 32313680, 2020). "Obesity might cause chronic inflammation via promoting the production of tumor-promoting cytokines such as IL-6 and activation of oncogenes such as STAT3, which has a critical role in regulating cell fate, inflammation, and immunity." (PMID 31988297, 2020). "Our finding reveals a critical role of CCL-2 and IL-6 in obesity-associated CNS inflammation and that may be potential therapeutic targets for prevention and treatment of obesity-related MS." (PMID 31507583, 2019). "There was a positive association for IL-6 and CRP in both sexes according to obesity (in the adjusted analysis); women who were obese in ≥ 2 follow-ups were associated with a mean IL-6 of 2.45 and a CRP of 3.74 compared to IL-6 of 1.21 and CRP of 1.29 for those with no exposures (adjusted analysis)." (PMID 31071114, 2019). "Among the factors that link obesity to carcinogenesis are the activation of the insulin/IGF-1 pathway, increased concentrations of pro-inflammatory cytokines (TNF-α, IL-1 and IL-6) and their influence on adipocytokines, and dyslipidemia, which is often associated only to obesity." (PMID 31703601, 2019).
Obesity (continued). "Obesity in cats, similar to other species, has been associated with decreased adipose tissue mRNA expression and circulating concentrations of adiponectin as well as increased adipose tissue expression of TNFα and IL6." (PMID 31492181, 2019). "It is important to emphasize that the increase of these cytokines, such as leptin and IL-6, establishes a pathophysiological link between increased adiposity and obesity-associated cardiovascular disease, insulin resistance, type 2 diabetes, hypertension, and dyslipidemia." (PMID 31489938, 2019). "Obesity was positively associated with IL-6 and CRP at all ages, in both sexes (p<0.001)." (PMID 31071114, 2019). "Collectively, these two studies provide clues regarding possible therapeutic targets for treatment of obesity and insulin resistance, implicating exercise-induced IL-6 may be required to achieve weight loss and improve glucose homeostasis." (PMID 31686269, 2019). "Obesity-associated inflammation has been proposed to play an important role underlying the differences in iron profiles between Ob and AW groups, perhaps through the induction of hepcidin production by cytokines such as IL-6 and leptin." (PMID 30909605, 2019). "Notably, increased IL-6 levels in obesity have been linked with metabolic inflammation, insulin resistance, and elevated circulatory CRP levels." (PMID 31718015, 2019). "An excess of pro-inflammatory adipokines (leptin, TNF-α, IL-6, etc.)may be responsible for the association between asthma and obesity." (PMID 31842862, 2019). "Arid5a is induced by the cytokines IL-6 and IL-17, and because IL-6 is a strong inducer of Arid5a, it is likely that IL-6-deficient mice have insufficient activation of Arid5a, which results in unrestricted adipogenesis and obesity." (PMID 31867000, 2019). "Higher circulating levels of IL6 have been associated with obesity and visceral adiposity." (PMID 31295854, 2019). "Last, we could not measure other obesity-associated adipokines such as other obesity-associated adipocytokines such as TNFα, leptin, IL6, IL8, MCP1, and FABP4 because of the limited quantity of samples." (PMID 32117043, 2019). "Therefore, obesity can cause chronic inflammation with enhanced proinflammatory cytokines IL-6 and CCL-2 production, which have the immune-enhancing effect to boost the effector Th1 and Th17 cell responses in HFD EAE." (PMID 31507583, 2019). "Moreover, IL-6 and TNFα levels have both been found to be increased in the serum of obese patients and are critical drivers of obesity-associated insulin resistance." (PMID 30787925, 2019). "An explanation for this association could be the fact that obesity might be considered as additional inflammation where pro-inflammatory adipokines, such as TNFα, IL1β, IL6 or MCP1, are segregated by adipose tissue and macrophages." (PMID 30786913, 2019). "After adjustment for age and sex, high IL-6 mRNA expression was also associated with obesity (AOR = 3.11, 95% CI = 1.74–5.56, p = 0.0001) and NAFLD (AOR = 2.59, 95% CI = 1.03–6.52, p = 0.042) and inversely associated with HBV (AOR = 0.34, 95% CI = 0.17–0.65, p = 0.0013)." (PMID 30034633, 2018). "Overall, understanding how IL-6 transmits signals to affect lipid metabolism in the heart might allow for development of better clinical therapies for obesity-associated cardiac lipotoxicity." (PMID 30134607, 2018). "The fact that that we found the same direction of the association between obesity/adiposity with IL-6 as well with CRP reinforces our findings in this cohort; moreover, the inverse association between adiposity with adiponectin also shows the consistency of this study." (PMID 29704817, 2018). "Collectively, obesity-associated increases of systemic TNFα and IL-6 might impact HCC initiation and progression via redundant and opposing functions of downstream signaling molecules." (PMID 30591653, 2018).
Obesity (continued). "Inflammatory markers associated with insulin resistance and obesity, such as interleukin-6 and C-reactive protein (CRP), may also contribute to functional decline by causing negative changes in the regulation of skeletal muscle homeostasis." (PMID 30032324, 2018). "An increase in the circulating TNF-α and IL-6 concentrations is associated with increased plasma glucose, body weight and BMI, which supports the idea that inflammatory cytokines play a role in the pathogenesis of diabetes and obesity." (PMID 30914847, 2018). "There is a close relationship between IL-6 and obesity-associated inflammation." (PMID 30374048, 2018). "To investigate whether clinical stages higher than I are associated with obesity, insulin resistance, and serum concentrations of adipokines, interleukin-6, and vitamin D, we applied logistic regression analysis." (PMID 30627158, 2018). "IL-6-deficient (IL-6−/−) mice displays obesity and insulin resistance compared with control mice." (PMID 30374048, 2018). "IL-6-deficient mice develop obesity and revert to normal once treated with IL-629." (PMID 29396550, 2018). "where skeletal muscle in obesity-associated type 2 diabetes develops a resistance to IL-6." (PMID 29342149, 2018). "Altogether these results led to the hypothesis that IL10, acting individually or jointly with IL6, could prevent or ameliorate obesity as well as associated IR and lipid disturbances." (PMID 30158466, 2018). "Furthermore, plasma IL-6 levels are elevated in patients with metabolic diseases such as obesity and T2D, which are linked to hepatic cell dysfunction and consequent insulin resistance." (PMID 29966345, 2018). "IL6 expression in adipose tissue, its positive association with obesity, systemic IR and inflammation is in agreement with our observations, but its role in obesity and chronic low-grade inflammation is poorly understood." (PMID 30242179, 2018). "Due to the ongoing epidemic of obesity in Brazil, the objective of this study was to assess in a cross-sectional and in a prospective way the association of different obesity measurements (BMI, WC and % FM) and IL-6, CRP and adiponectin at 22 years, in a population Birth Cohort in Southern Brazil." (PMID 29704817, 2018). "Two health behavior factors, obesity and smoking status, were independently associated with IL-6." (PMID 29951282, 2018). "Additionally, similar to obesity is the upregulation of factors like TNFα and IL-6 that are implicated in the development of insulin resistance and glucose intolerance." (PMID 28212318, 2017). "Obesity in patients was associated with a marked increase in IL-6 and CRP levels." (PMID 28103807, 2017). "Although the underlying mechanisms linking obesity to hepatic lipid accumulation and IR are incompletely understood, TNFα and IL-6 production in adipose tissue are critical for the development of steatohepatitis and NFκB has been recognized as an obligatory mediator of most of these TNFα responses." (PMID 29170528, 2017). "Increased levels of IL-6 are associated with obesity, T2D, and cardiovascular disease." (PMID 29163354, 2017). "Psoriasis and obesity are both characterized by overexpression of key proinflammatory cytokines, hsCRP and IL-6, which have been accepted as classical markers of CVD risk and are therefore valuable markers for the assessment of the cardiovascular status of patients with PS." (PMID 28947858, 2017). "Growing evidence reveals that the accumulation of adipose tissue leads to the development of systemic inflammation (e.g. increases in circulating levels of tumor necrosis factor-α and interleukin-6), which accounts for the obesity-associated vasculopathy and cardiovascular risks." (PMID 28738856, 2017).